GSDMD (gasdermin D)
Diseases named in the same sentence as GSDMD in open-access papers (continued):
Sharing a sentence is not in itself a finding about the gene and the disease.
colitis (continued). "Bacteroides fragilis‐derived outer membrane vesicles deliver miR‐5119 and alleviate colitis by targeting PD‐L1 to inhibit GSDMD‐mediated neutrophil extracellular trap formation." (PMID 40558568, 2025). "To further investigate the role of GSDMD in NDGA-mediated protection against colitis, we utilized GSDMDfl/flLyz2-Cre mice." (PMID 40596758, 2025). "In experimental colitis, GSDMD in colonic epithelial cells is activated via the caspase-8 inflammasome signaling pathway, facilitating the release of IL-1β through the non-lytic vesicle pathway." (PMID 39994107, 2025). "In one of these reports, it was shown that GSDMD-derived pores promotes colitis via IL-18 secretion from IECs3." (PMID 39489845, 2024). "Protein mediators involved in the multiple inflammasome pathways that activate GSDMD, including NLRP1, NLRP3, and AIM2, have been shown to attenuate the development of colitis-associated colorectal cancer (CAC) in mice." (PMID 38898209, 2024). "Immunoblotting analysis showed substantially increased caspase-1 p20 and GSDMD-NT in colonic tissues from colitis mice relative to water control mice." (PMID 39113799, 2024). "Patients with IBD and mice models of colitis display high levels of GSDMD in the intestinal epithelial cells." (PMID 37891577, 2023). "Opposing evidence reported that GSDMD plays protective roles in IBD, since genetic ablation of GSDMD aggravated colitis by boosting cyclic GMP-AMP synthase (cGAS)-dependent inflammation." (PMID 37891577, 2023). "Pyroptosis has recently been verified as a critical cell death pathway in colitis, and caspase-1/GSDMD-mediated pyroptosis is an inflammatory cell death process that has become a novel target for UC treatment." (PMID 37580819, 2023). "VAD mice demonstrated severe experimental colitis and increased expression of inflammasome-related proteins (caspase-11, GSDMD, NLRP3, ASC, caspase-1, IL-1β, and IL-18) in the colonic LP." (PMID 37240022, 2023). "Collectively, these results suggest that DCA exacerbates TNBS-induced colitis by activating GSDMD-dependent pyroptosis and IL-1β secretion." (PMID 37131223, 2023). "Taken together, SIT did ameliorate experimental colitis by inhibiting the NLRP3/Caspase-1/GSDMD-dependent pyroptosis pathway." (PMID 37954856, 2023). "The expression of GSDMD is increased in IECs from both DSS-induced colitis mice and IBD patients, and GSDMD deficiency effectively reduces the severity of DSS-induced colitis." (PMID 37275856, 2023). "In this context, IBD patients and animals subjected to experimental colitis showed increased epithelial GSDMD expression and genetic ablation of GSDMD attenuated colitis severity in mice." (PMID 35264769, 2022). "In the murine model of colitis, GSDMD is activated during intestinal inflammation and is confirmed as a negative regulator controlling cyclic GMP-AMP synthase (cGAS)–dependent inflammation, providing a new clue to restrain colitis by regulating GSDMD." (PMID 35774778, 2022). "Roseburia intestinalis, a butyrate−producing bacterium, -derived flagellin was demonstrated to inhibit the activation of NLRP3/caspase-1/GSDMD signaling-triggered pyroptosis in macrophages by targeting miR−223−3p and ameliorate colitis." (PMID 36505474, 2022). "Accordingly, GSDMD is upregulated in the colon of colitis mice and mucosal biopsies from IBD patients." (PMID 35264769, 2022). "Increased expression and processing of caspase-11 and GSDMD were observed during DSS-induced colitis." (PMID 35712726, 2022). "Gly-Pro-Ala (GPA), a GPA peptide isolated from fish skin gelatin hydrolysate, ameliorate DSS-induced colitis by inhibiting GSDMD-mediates pyroptosis." (PMID 35677444, 2022). "For instance, GSDMD plays a crucial role in limiting experimental colitis by restricting cGAS-dependent inflammation." (PMID 35455985, 2022). "Patients with IBD and experimental colitis exhibit increased expression of epithelial-derived GSDMD, suggesting a potential role for GSDMD in IBD." (PMID 35677444, 2022).
colitis (continued). "GSDMD is activated by the dysregulated microbiota and in turn mediates microbiota-driven colitis by promoting IL-18 release." (PMID 34721422, 2021). "To investigate which cell populations are critical for GSDMD-mediated colitis promotion, we used a bone-barrow transfer assay to generate GSDMD bone-barrow chimeras." (PMID 34721422, 2021). "Our study provides a novel mechanism for microbiota-mediated colitis development by activating GSDMD and suggests that GSDMD is a promising target for IBD therapy." (PMID 34721422, 2021). "Collectively, our data suggest that dysregulated commensal E. coli mediates GSDMD activation, which in turn promotes colitis development." (PMID 34721422, 2021). "We found that Adv-GSDMD-C obviously suppressed colitis development, suggesting that GSDMD activation is required for GSDMD-mediated colitis development." (PMID 34721422, 2021). "Collectively, these data indicate that GSDMD expression in IECs is critical for GSDMD-mediated colitis promotion." (PMID 34721422, 2021). "Together, our data suggest that GSDMD promotes IL-18 release during colitis; and that the released IL-18 mediates colitis development by promoting goblet cell loss." (PMID 34721422, 2021). "Our results provide a potential molecular mechanism by which the microbiota-driven GSDMD activation contributes to colitis pathogenesis." (PMID 34721422, 2021). "Collectively, these data suggest that GSDMD promotes IL-18 release during colitis; and that the activation of GSDMD is required for its release." (PMID 34721422, 2021). "Here, we indicated that dysregulated microbiota-driven GSDMD activation promoted colitis development by inducing IL-18 release." (PMID 34721422, 2021). "Increased expression of epithelial GSDMD is observed in patients with IBD and experimental colitis model animals, and the epithelial-derived GSDMD mediates the release of insoluble IL-1β during experimental colitis." (PMID 34683937, 2021). "Collectively, these data suggested that the microbiota was dysregulated during colitis; and that the dysregulated microbiota, particularly E. coli, mediated colitis development by activating GSDMD." (PMID 34721422, 2021). "To determine which cell populations are critical for GSDMD-mediated DSS-induced colitis, we generated four groups of GSDMD bone marrow chimeras." (PMID 34721422, 2021). "Full‐length caspase‐11 and caspase‐1, as well as processed caspase‐11 (p26), caspase‐1 (p20), and GSDMD (p30, a marker of cell pyroptosis), were elevated on day 7 in colon tissue of GPx8−/− mice with colitis compared with samples from WT mice." (PMID 31782617, 2020). "However, in conditions such as colitis, GSDMD also plays a protective role by preventing epithelial damage and colitis onset." (PMID 39994107, 2025). "One report showed that GSDMD deficiency protects mice from dextran sulfate sodium (DSS)-induced colitis, whereas another report found that GSDMD exhibited anti-inflammatory effects in this chemically induced colitis model." (PMID 40103680, 2025). "Additionally, macrophage-specific deletion of GSDMD exacerbates colitis by enhancing cyclic GMP-AMP synthase-mediated inflammatory responses." (PMID 40041420, 2025). "Deletion of GSDMD in macrophages significantly diminished the protective effect of NDGA on colitis." (PMID 40596758, 2025). "Moreover, we observed that colonic tissues of mice with colitis had elevated levels of GSDMD expression, which was significantly diminished in mice treated with Bf‐OMVs and miR‐5119." (PMID 40558568, 2025). "Similarly, neutrophils in the colons of mice with colitis treated with B. fragilis and BfOMVs+ displayed significant downregulation of GSDMD expression, with the BfOMVs+ group showing a more pronounced effect." (PMID 40558568, 2025). "GSDMD was found to repress tumor development in a mouse model of colitis-associated colon cancer, which was attributed to its role in protecting mice from DSS-induced colitis." (PMID 38898209, 2024).
colitis (continued). "GSDMD-mediated macrophage pyroptosis aggravates experimental colitis in mice." (PMID 39253076, 2024). "GSDMD−/− murine model of DSS-induced colitis co-treated with RU." (PMID 39050748, 2024). "For example, Karki study showed that knockdown of interferon regulatory factor 1 could significantly inhibit the activation of GSDMD (pyroptosis), CASP3/7 (apoptosis) and MLKL (necroptosis), thereby promoting cell death in colitis-associated CRC." (PMID 39331898, 2024). "Furthermore, another study indicates that GSDMD-mediated pyroptosis and inflammation potentially precede necroptosis during intestinal inflammation, contributory to the development of colitis." (PMID 39253076, 2024). "Additionally, our previous study found that GSDMD in intestinal macrophages controlled colitis by regulating cGAS-mediated inflammatory responses." (PMID 38807373, 2024). "This study showed that T.s could alleviate the pathological severity UC via GSDMD-mediated pyroptosis and provides new insight into the mechanism study and application of helminths in treating colitis." (PMID 37580819, 2023). "Moreover, DCA administration aggravated TNBS-induced colitis by promoting Gasdermin D (GSDMD)-mediated pyroptosis and IL-1beta (IL-1β) production in macrophages." (PMID 37131223, 2023). "Furthermore, knocking down GSDMD in mice considerably eliminated DCA’s pro-inflammatory action in experimental colitis." (PMID 37131223, 2023). "This study showed that T.s could alleviate the pathological severity UC via GSDMD-mediated pyroptosis, and it provides new insight into the mechanistic study and application of helminths in treating colitis." (PMID 37580819, 2023). "In addition, our study found that Forsythia suspensa extract can inhibit the protein and gene expression levels of NLRP3, ASC, Caspase-1 and GSDMD in colitis mice." (PMID 35326124, 2022). "The protective effect of GSDMD in macrophages against DSS-induced colitis has been demonstrated." (PMID 35677444, 2022). "Evidence also suggests that GSDMD plays a protective role in DSS-induced colitis." (PMID 35677444, 2022). "In our study, we found that GSDMD was activated in DSS-induced colitis." (PMID 34721422, 2021). "To investigate whether the activation of GSDMD is required for GSDMD-mediated colitis development, we used Adv-mediated GSDMD-C expression, which suppressed GSDMD-mediated cell pyroptosis by binding GSDMD-N, in WT mouse colons." (PMID 34721422, 2021). "Because antimicrobial peptides (AMPs) are critical in maintaining mucosal barrier integrity and suppressing colitis development, we investigated whether GSDMD promotes colitis by decreasing AMP production." (PMID 34721422, 2021). "Thus, GSDMD promotes colitis development by mediating IL-18 release, and the microbiota can mediate colitis pathogenesis through regulation of GSDMD activation." (PMID 34721422, 2021). "Here, we found that gasdermin D (GSDMD) was activated during acute colitis." (PMID 34721422, 2021). "Moreover, commensal Escherichia coli (E. coli) largely overgrew during colitis, and then the dysregulated commensal E. coli mediated GSDMD activation." (PMID 34721422, 2021). "GSDMD deficiency reduced IEC proliferation and IEC death in DSS-induced colitis." (PMID 34721422, 2021). "In the colitis model, mice GSDMD can relieve intestinal inflammatory symptoms by inhibiting the cGAS-STING signaling pathway, and this process has nothing to do with intestinal flora and is mainly induced by K+ outflow caused by GSDMD pore formation in the cytomembrane." (PMID 34899666, 2021). "In addition to enhancing pyroptosis, GSDMD in colonic macrophages regulates cGAS-mediated inflammatory responses, which protect against intestinal bacterial invasion and epithelial damage following mucosal barrier disruption, thus mitigating colitis." (PMID 39994107, 2025). "Therefore, we hypothesized that GSDMD inhibitor treatment in LRRK2 G2019S KI mice will reduce DSS-induced colitis." (PMID 38607004, 2024).
colitis (continued). "Notably, GSDMD inhibitors attenuate colitis in LRRK2 G2019S KI mice." (PMID 38607004, 2024). "Importantly, the deletion of GSDMD effectively restrains the effect of DCA on TNBS-induced colitis." (PMID 37131223, 2023). "We tested this hypothesis by administering DCA to GSDMD-KO mice and induced colitis using TNBS." (PMID 37131223, 2023). "Next, we asked whether GSDMD plays an important role in colitis development." (PMID 34721422, 2021). "Moreover, to determine whether GSDMD affects IEC proliferation or IEC death during colitis, we analyzed intestinal cell proliferation and cell death by Ki67 and TUNEL staining, respectively." (PMID 34721422, 2021). "Next, we checked whether GSDMD affects goblet cell damage during DSS-induced colitis." (PMID 34721422, 2021). "We asked whether GSDMD promotes IL-18 release during colitis." (PMID 34721422, 2021). "Therefore, we asked whether the activation of GSDMD is regulated by dysregulated gut microbiota during DSS-induced colitis." (PMID 34721422, 2021). "Next, we investigated whether GSDMD is involved in microbiota-driven colitis development." (PMID 34721422, 2021). "Interestingly, a very recent study could show that Gasdermin D in macrophages is necessary to protect from exacerbated colitis in a murine model of experimentally induced colitis." (PMID 32987848, 2020). "DMB‐driven GSDMD activation substantially attenuated miR‐5119′s inhibitory effects on NET formation and attenuated its therapeutic efficacy in colitis." (PMID 40558568, 2025). "Mechanistically, Bf‐OMVs are enriched with miR‐5119, which targets and inhibits PD‐L1, leading to the suppression of GSDMD‐mediated NET release, thereby alleviating colitis." (PMID 40558568, 2025). "Specifically, Bf‐OMVs are enriched with miR‐5119, which targets and inhibits PD‐L1, leading to the suppression of GSDMD‐mediated NET release and then colitis alleviation." (PMID 40558568, 2025). "Confirming that miR‐5119 inhibits NET formation by targeting PD‐L1 to downregulate GSDMD‐mediated NET release, thereby alleviating DSS‐induced colitis." (PMID 40558568, 2025). "Treating G2019S KI mice with the GSDMD inhibitors disulfiram and DMF significantly attenuated DSS-induced colitis, comparable to WT control mice." (PMID 38607004, 2024). "Gasdermin D (GSDMD), a key executioner of pyroptosis downstream of the inflammasome, has been found to play intricate roles in modulating colitis by influencing intestinal macrophages and regulating mucus secretion from goblet cells." (PMID 38807373, 2024). "To test the distinct impacts of disulfiram and DMF on GSDMD processing in vivo, we collected IECs from the colon after DSS colitis induction and analyzed the caspase-1 cleavage and GSDMD cleavage by Western blotting." (PMID 38607004, 2024). "provided clues to suggest that GSDMD acts as a negative regulator of cyclic GMP–AMP synthase-dependent inflammation in macrophages, therefore conferring protective effect against colitis." (PMID 39253076, 2024). "The results showed that the mRNA expression levels of NLRP3, GSDMD and NF-κB were highly expressed in the colon tissues of DSS-induced colitis and significantly decreased in the T.s intervention groups." (PMID 37580819, 2023). "In a DSS-induced mouse colitis model, the use of VX765 (a caspase-1 inhibitor), which inhibits caspase-1/GSDMD pathway-regulated pyroptosis, attenuates colitis in mice." (PMID 35677444, 2022). "The mRNA expressions of NLRP3, ASC, caspase-1, GSDMD, IL-18, and HMGB1 were shown to increase in different extents in colitis tissues than in control tissues, whereas SM934 treatment decreased the expression of these genes." (PMID 36120344, 2022). "In the DSS-induced colitis mouse model, overgrowth of commensal E. coli, which mediated the activation of GSDMD in IEC (GSDMD was strongly cleaved to activated GSDMDNT) promoted pyroptosis." (PMID 35677444, 2022).
colitis (continued). "These examples above illustrate that GSDMD mediated pyroptosis and IBD are closely related and can be regulated by modulating GSDMD-mediated pyroptosis in a DSS-induced colitis model." (PMID 35677444, 2022). "Furthermore, the activated GSDMD promoted the release of interleukin-18 (IL-18), but not the transcript or maturation level of IL-18, which in turn mediated goblet cell loss to induce colitis development." (PMID 34721422, 2021). "Herein, our study found that dysregulated microbiota activated GSDMD, which in turn mediated DSS-induced colitis development by promoting IL-18 release." (PMID 34721422, 2021). "Furthermore, MHV-68 infection activated pyroptosis by upregulating gasdermin D, NLRP3, interleukin-1β, and interleukin-18 in colonic tissues and peritoneal macrophages of mice with colitis." (PMID 40041420, 2025). "Similarly, in DSS-induced colitis, MHV-68 infection resulted in significant expression of GSDMD, NLRP3, IL-1β, and IL-18 in peritoneal macrophages." (PMID 40041420, 2025). "DMB‐driven GSDMD activation and GSDMD overexpression with plasmids substantially attenuated miR‐5119′s inhibitory effects on NET formation, and compromised its therapeutic efficacy in alleviating colitis." (PMID 40558568, 2025). "To further validate the mechanism by which IMP alleviates GSDMD-mediated macrophage pyroptosis via AIM2 in mice, we performed double immunofluorescence staining for F4/80 and AIM2 on colon tissues from IMP-treated TNBS-induced colitis (CD) mice." (PMID 40915382, 2025). "In striking contrast, a different publication showed that in experimental colitis, GSDMD plays a protective role in macrophages but not in IECs4." (PMID 39489845, 2024). "We observed increased GSDMC mRNA expression in IBD patients and cleavage of GSDMC was upregulated in experimental colitis mice, suggesting that GSDMC may be involved in IBD, similarly to GSDME and GSDMD." (PMID 37740137, 2023). "GSDMD in macrophages but not epithelial cells protects against DSS-induced colitis, and GSDMD deficiency causes more severe DSS colitis." (PMID 37275856, 2023). "The non-canonical inflammasome, comprising murine caspase-11 (or the human orthologs caspase-4/5) and GSDMD, has a protective role against Gram-negative bacterial infection; however, little is known regarding its function in colitis." (PMID 37240022, 2023). "Indeed, GSDMD functions in macrophages are a negative regulator of cGAS-STING-dependent inflammation, thereby protecting against colitis." (PMID 37566032, 2023). "It is found that GSDMD in IECs, but not infiltrating immune cells, was activated by dysregulated commensal and in turn modulated microbiota-driven colitis by promoting IL-18 release form pyroptotic cell death." (PMID 36505474, 2022). "It is recently found that 10-hydroxy-2-decenoic acid (10-HDA), the most abundant fatty acid and major lipid component in royal jelly, alleviated DSS-induced colitis and enhancing colonic barrier function by regulating the NLRP3/caspase-1/GSDMD-mediated pyroptotic pathway." (PMID 36505474, 2022). "Irradiated WT recipient mice receiving WT or Gsdmd-/- bone marrow had similar body weight loss, clinical score, colon length, and histological damage, suggesting that gut-infiltrating immune cells are not important for GSDMD-mediated colitis promotion." (PMID 34721422, 2021). "Mechanistically, GSDMD expression in intestinal epithelial cells (IECs), but not infiltrating immune cells, was critical for GSDMD-mediated colitis progression." (PMID 34721422, 2021). "Our data showed that GSDMD in IECs was responsible for GSDMD-mediated colitis promotion, while gut infiltrating immune cell-derived GSDMD was not involved in this process." (PMID 34721422, 2021). "Some researchers demonstrated a noncritical role of the gut microbial community as cohousing with WT mice did not change the impact of Gsdmd depletion on colitis, while others suggested that the gut microbiome partially mediated the effect of GSDMD in HFD-fed mice." (PMID 35972273, 2022).